KISS1 (KiSS-1 metastasis suppressor)
Diseases named in the same sentence as KISS1 in open-access papers (continued):
Sharing a sentence is not in itself a finding about the gene and the disease.
pancreatic cancer (3 papers, 2009 to 2026). "Based on the results, the authors concluded that KISS1 therapy might prove beneficial in suppressing the metastasis of pancreatic cancer." (PMID 30123188, 2018). "We hypothesized high levels of KiSS-1 and GPR54 expression could be associated with better survival of pancreatic cancer patients." (PMID 19154616, 2009). "We previously found that expression of KiSS-1 mRNA was lower and expression of GPR54 mRNA was higher in pancreatic cancer tissue compared with normal pancreatic tissue." (PMID 19154616, 2009). "However, the clinical significance of KiSS-1 and GPR54 expression by pancreatic cancer remains unclear." (PMID 19154616, 2009).
renal cell carcinoma (3 papers, 2015 to 2021). "Moreover, siRNA-TCF21 downregulates the expression of KISS1 and the invasion ability in Cak-1 cells, suggesting that aberrantly expressed miR-21 regulates the invasion pathway through TCF21-KISS1 association in renal cell carcinoma." (PMID 33729392, 2021). "Honokiol inhibits the migration of renal cell carcinoma through activation of the RhoA/ROCK/MLC signaling pathway and by targeting KISS1/KISS1R signaling." (PMID 34671554, 2021).
choriocarcinoma (2 papers, 2022). An aggressive malignant tumor arising from trophoblastic cells. "Additionally, low KISS1/KISS1R expression was described in the highly invasive trophoblast cells of choriocarcinoma, while high KISS1/KISS1R expression was reported in the non-invasive cells of benign molar pregnancies." (PMID 37538930, 2022). "Thus, kisspeptin levels can be altered in choriocarcinomas and other GTDs, which is interesting when considering the original identification of KISS-1 as an anti-metastatic gene." (PMID 35928889, 2022).
clear cell renal cell carcinoma (2 papers, 2022 to 2025). "In clear cell renal cell carcinoma, TP73-AS1 silencing suppressed cell proliferation and promoted apoptosis in vitro through the upregulation of KISS1 expression and the activation of PI3K/Akt/mTOR signaling." (PMID 35614413, 2022). "In clear-cell renal cell carcinoma, TP73-AS1 interacts with Enhancer of zest homolog 2 (EZH2) and then specifically binds to the promoter region of the KISS1 gene, thereby inhibiting the expression of KISS1 and ultimately promoting cell proliferation and migration." (PMID 40332793, 2025).
colon adenocarcinoma (2 papers, 2018 to 2026). "The purpose of the current study is to assess the expression of MACC1, CD44, Twist1, and KiSS-1 in the colonic adenocarcinoma (CAC) tissues of patients and their associations between pathological characteristics and prognosis of patients with CAC." (PMID 30021598, 2018). "However, the associations of MACC1, CD44, Twist1, and KiSS-1 in colonic adenocarcinoma (CAC) invasion and metastasis remain unclear." (PMID 30021598, 2018).
cryptorchidism (2 papers, 2020 to 2022). The failure of one or both testes of a male fetus to descend from the abdomen into the scrotum during the late part of pregnancy. "In this study, one pig presented unilateral cryptorchidism, but its frequency of KISS1-disruptive alleles was considerably lower (60%) than that of KISS1 KO boars (100%)." (PMID 36685939, 2022). "Cryptorchidism is one of the most common congenital defects in pigs and it that impaired testicular descent of boar 53MY is likely unrelated to KISS1 disruption." (PMID 36685939, 2022).
depression (2 papers, 2022 to 2025). "- A decrease in E2 suppresses Kiss1 gene expression, increasing the risk of emotional instability.- An increase in E2 significantly enhances Kiss1 expression, reducing the risk of depression." (PMID 39935532, 2025).
endometrial cancer (2 papers, 2012 to 2023). Primary or metastatic malignant neoplasm involving the endometrium (mucous membrane that lines the endometrial cavity). "GPR54 is a gene-encoding endogenous receptor of kisspeptin (KISS1), a suppressor of cancer metastasis, and has reduced expression in some cancers, but an unclear status in endometrial cancer." (PMID 22548175, 2012).
fertility disorders (2 papers, 2016 to 2025). "The phenotype of the mutant mice is as expected from a Kiss1 null mutation; namely, an absence of sexual maturation and sterility in both sexes." (PMID 27663274, 2016).
fetal growth restriction (2 papers, 2024). A fetus that does not grow beyond the 10th percentile of conventionally accepted weight for gestational age. "Furthermore, a decreased maternal KISS1 has been correlated with fetal growth restriction." (PMID 38397936, 2024).
gestational diabetes (2 papers, 2022 to 2024). Carbohydrate intolerance first diagnosed during pregnancy. "KISS1 and NKB levels increase in pregnancy due to placental production, and these peptides along with neurokinin receptors have been implicated in the pathogenesis of several pregnancy complications (PE, gestational diabetes, intrauterine growth restriction (IUGR), and preterm delivery)." (PMID 38397936, 2024).
Hyperglycemia (2 papers, 2018 to 2022). An increased concentration of glucose in the blood. "On the contrary, another paper in the same year reported inhibition of Kiss1 attenuated hyperglycemia." (PMID 29593567, 2018). "Another study in Cell Metabolism reported that inhibition to Kiss1 led to attenuated hyperglycemia but no change in body weight." (PMID 29593567, 2018).
nasopharyngeal carcinoma (2 papers, 2020 to 2021). A carcinoma arising from the nasopharyngeal epithelium. "Previous works in our laboratory showed that KISS1 gene suppresses metastasis of nasopharyngeal cancer via activation of the ERK1/2 pathway." (PMID 35117986, 2021). "Therefore, overexpression of KISS1 is not only the underlying pathological cause of dysregulation of LKB1, but it is also related to the proliferation of nasopharyngeal carcinoma via activated LKB1/AMPK pathway." (PMID 35117986, 2021). "At the same time, the expression levels of KISS1 and KISS1R are positively correlated with the differentiation degree of cells in the nasopharyngeal carcinoma cell line, indicated by RT-PCR and western blotting." (PMID 35117986, 2021). "The western blot protein expression analysis revealed that KISS1 and KISS1R were also lowly expressed in poorly differentiated nasopharyngeal carcinoma cells compared with well differentiated nasopharyngeal carcinoma cells." (PMID 35117986, 2021). "Taken together, the current study illustrates a molecular and signal pathway basis for better understanding of how KISS1/KISS1R alters LKB1 activation and thereby activates the AMPK signaling pathway, ultimately inhibits the proliferation of nasopharyngeal carcinoma." (PMID 35117986, 2021). "The RT-PCR analysis revealed that compared with well differentiated nasopharyngeal carcinoma cells, such as CNE-1 cells and HK-1 cells, the mRNA of KISS1 and KISS1R were lowly expressed in poorly differentiated nasopharyngeal carcinoma cells, such as HNE1 cells and 5-8F cells." (PMID 35117986, 2021). "However, whether the KISS1 gene and its receptor KISS1R gene are involved in the regulation and how to regulate the proliferation mechanism of nasopharyngeal carcinoma is unclear." (PMID 35117986, 2021). "Due to the lack of studies evaluating the role of KISS1 and KISS1R in the proliferation of nasopharyngeal carcinoma cells, we have tried to assess its role and molecular mechanism in nasopharyngeal carcinoma progression." (PMID 35117986, 2021).
pyometra (2 papers, 2023 to 2024). "Furthermore, this study showed a positive correlation between the expression of genes KISS1 and KISS1R in the uterus of cats and reported that the pyometra, a major uterine inflammatory disease in female cats, increases endometrial protein expression of Kiss1 and Kiss1r." (PMID 37835759, 2023).
renal carcinoma (2 papers, 2016 to 2021). A carcinoma arising from the epithelium of the renal parenchyma or the renal pelvis. "In renal cancer, the expression of KISS-1 was downregulated with TCF21 gene silencing." (PMID 35201460, 2021).
abortion (1 paper, 2023). the ending of pregnancy by removing a fetus or embryo before it can survive outside the uterus. "The MAPK/ERK signaling pathway is reported to be regulated intracellularly by KISS-1, and KISS-1 is associated with abortion, cell proliferation and migration." (PMID 37024487, 2023).
benign ovary tumors (1 paper, 2017). "Levels of VM, ALDH1, and MACC1 were significantly higher, and levels of KiSS-1 significantly lower, in EOC tissues than in benign ovary tumors." (PMID 28253891, 2017).
colorectal adenocarcinoma (1 paper, 2018). The most common type of colorectal carcinoma. "The analysis of KiSS-1 and KiSS-1R expression in normal and malignant tissue samples from 111 patients with colorectal adenocarcinoma showed that KiSS-1 expression levels were much higher in the normal than in the malignant colonic mucosa." (PMID 29760678, 2018).
congenital hypogonadotropic hypogonadism (1 paper, 2025). Congenital hypogonadotropic hypogonadism (CHH) is a rare disorder of sexual maturation characterized by gonadotropin (Gn) deficiency with low sex steroid levels associated with low levels of follicle stimulating hormone (FSH) and luteinizing hormone (LH). "Inactivating mutations in the kisspeptin (Kiss1) gene or its receptor (Kiss1r) result in congenital hypogonadotropic hypogonadism and failure to progress through puberty in humans and mice." (PMID 40276575, 2025).
fibrosarcoma (1 paper, 2011). A malignant mesenchymal fibroblastic neoplasm affecting the soft tissue and bone. "Conversely, it has been reported that in HT-1080 human fibrosarcoma cells where Kp signaling is anti-invasive, expression of KISS1 results in the negative regulation of MMP-9 production." (PMID 21738726, 2011).
glioblastoma (1 paper, 2023). The most malignant astrocytic tumor (WHO grade IV). "For instance, its expression in the brain is not favorable for patients during the development of glioblastoma, as KISS1 has been shown to accelerate the metastatic ability of glioblastoma through the Gq-PLC-PKC pathway." (PMID 36766779, 2023).
hemangioma (1 paper, 2018). A benign vascular lesion characterized by the formation of capillary-sized or cavernous vascular channels. "In a previous study, Kiss1 metastasis-suppressor (Kiss1) was underexpressed in endothelial cells isolated from human hemangioma tissue." (PMID 29652858, 2018).
Hirsutism (1 paper, 2020). Abnormally increased hair growth referring to a male pattern of body hair (androgenic hair). "Hormonal, metabolic profiles, and hirsutism scores, as well as serum kisspeptin level, were assessed by using Human Kisspeptin 1(KISS-1) ELISA Kit." (PMID 33061987, 2020).
Hypertension (1 paper, 2024). The presence of chronic increased pressure in the systemic arterial system. "To further characterize the potential underlying causes of hypertension, hypertrophy, and fibrosis development in CKD, we measured the renal expressions of Kiss1 and Agtr2 genes as well as ACE activity and the serum levels of para-cresyl sulfate and indoxyl sulfate." (PMID 37987885, 2024).
hyperthyroidism (1 paper, 2017). Overactivity of the thyroid gland resulting in overproduction of thyroid hormone and increased metabolic rate. "In hyperthyroidism, reduction of the inhibitory factor GnIH may have little impact on downstream regulation, whereas reduction of Kiss1 may dominantly contribute to decrease LH levels." (PMID 28432332, 2017).
Hypoglycemia (1 paper, 2020). A decreased concentration of glucose in the blood. "Loss of Prkar1a in the Sur1-/- mouse model of KATP hyperinsulinism significantly attenuated fasting induced hypoglycemia, decreased the insulin/glucose ratio, and also increased the hepatic expression of Kiss1 by more than 10-fold." (PMID 32735622, 2020).
hypothalamic hamartoma (1 paper, 2023). "CPP may incorporate genetic alterations, such as MKRN3, DLK1, and KISS1; mutations in the epigenetic factors that regulate the HPG axis, such as Lin28b and Let 7; syndromes; central lesions such as hypothalamic hamartoma; and others." (PMID 38021712, 2023). "CPP may occur as genetic alterations, such as MKRN3, DLK1, or KISS1;as a part of mutations in the epigenetic factors that regulate the HPG axis, such as Lin28b and let-7; or as a part of syndromes, central lesions such as hypothalamic hamartoma, and others." (PMID 38021712, 2023).
invasive breast carcinoma (1 paper, 2018). A carcinoma that infiltrates the breast parenchyma. "The analysis of KiSS-1 mRNA levels in fresh frozen tissue samples from ductal invasive breast carcinomas revealed a significant reduction of KiSS-1 expression in brain metastases as compared to the primary tumors." (PMID 29760678, 2018).
invasive ductal carcinoma (1 paper, 2018). "We found localization of KISS1 and KISS1R in invasive ductal carcinoma tumors using immunostaining." (PMID 30123188, 2018). "Using immunohistochemistry, studies have shown that KISS1 and KISS1R is localized within the ductal carcinoma in situ and in invasive ductal carcinoma, and that there was higher cytoplasmic staining in tumors as well as surrounding cells, compared to normal tissue." (PMID 30123188, 2018).
ischemia (1 paper, 2022). A hypoperfusion of the BLOOD through an organ or tissue caused by a PATHOLOGIC CONSTRICTION or obstruction of its BLOOD VESSELS, or an absence of BLOOD CIRCULATION. "NA depletion was reported to improve brain recovery from ischemia-induced damage in rats, and additionally, NA was found to modulate the Kiss1 transcript, Kiss protein levels, by acting on α-1 adrenergic receptors." (PMID 36422497, 2022).
liver cancer (1 paper, 2018). An epithelial or non-epithelial malignant neoplasm that arises from the liver. "Since then, it has become apparent that KISS1, KPs, and KISS1R regulate the development and progression of several cancers but interestingly, while these molecules act as suppressors of tumorigenesis and metastasis in many cancers, in breast and liver cancer they function as promoters." (PMID 30123188, 2018).
liver disease (1 paper, 2022). "Overall, the data suggest that the KISS1/KISS1R signaling pathway is enhanced in patients with liver disease, possibly as an adaptive mechanism in response to injury of the liver." (PMID 35349482, 2022).
malnutrition (1 paper, 2022). Inadequate nutrition resulting from poor diet, malabsorption, or abnormal nutrient distribution. "Insulin is a signal that links metabolism with reproduction, particularly since Kiss1 neurons are sensitive to circulating metabolic signals such as leptin and insulin, which confirms their importance in mediating the body’s response to nutrition or malnutrition." (PMID 36297033, 2022).
memory impairment (1 paper, 2020). "In mice, Kiss1 peptide (kisspeptin-13) enhances memory including passive avoidance memory consolidation and also mitigates memory impairment induced by Amyloid-β55,56, suggesting possible link between Kiss1 and dopaminergic signalling." (PMID 33168887, 2020).
mesothelioma (1 paper, 2018). A usually malignant and aggressive neoplasm of the mesothelium which is often associated with exposure to asbestos. "The purpose of this work is to study the role of KiSS1 in mesothelioma and to define the pathway involved in cancer progression or survival." (PMID 29721201, 2018). "We studied the role of KiSS1 on proliferation, invasiveness, migration abilities of mesothelioma cell lines focusing on the effect on epithelial-to-mesenchymal transition (EMT)." (PMID 29721201, 2018). "To study the role of Kisspeptin and its G-protein coupled receptor GPR54 in mesothelioma, we first evaluated the expression level of KiSS1 and GPR54 in human mesothelioma cell lines." (PMID 29721201, 2018). "Quantitative expression of KiSS1 and GPR54 was detected by qPCR and Western Blot analysis on total RNA and protein from mesothelioma cell lines, respectively." (PMID 29721201, 2018). "Our results support anti-proliferative effect of KiSS1 in cancer cells and suggest that targeting the KiSS1/GPR54 system may represent a novel therapeutic approach for mesothelioma." (PMID 29721201, 2018). "First of all, we checked the presence of transcripts and proteins of KiSS1 and its coupled receptor, GPR54, in mesothelioma cell lines H2452, H28 and MSTO observing a prevalence of expression levels in H2452 and H28 lines, epithelial and sarcomatoid mesothelioma, respectively." (PMID 29721201, 2018).
metastasis (1 paper, 2024). The spread or migration of cancer cells from one part of the body (where they first appeared) to another. "KiSS-1 is a gene that encodes a protein called kisspeptin, which plays a crucial role in various physiological processes, particularly in the regulation of puberty and reproduction, and was originally identified as a metastasis suppressor gene." (PMID 39858430, 2024).
metastatic cancers (1 paper, 2023). A carcinoma which has spread from the original site of growth to another anatomic site. "When used in conjunction with oncolytic virotherapy for the treatment of breast and other metastatic cancers, KISS1 transgenic expression has the potential to be an efficient tool for CRAd-mediated cytotoxicity in BC cells." (PMID 37970212, 2023).
metastatic prostate carcinoma (1 paper, 2018). A carcinoma that arises from the prostate gland and has spread to other anatomic sites. "Only in metastatic prostate cancer patients, a preliminary data that increased expression of KiSS-1 is able to sensitize cancer cells to chemotherapies; in the same setting of patients, expression of KiSS-1 is inversely correlated with tumor differentiation and clinical staging." (PMID 29662466, 2018).
multiple myeloma (1 paper, 2018). "In fact, KISS1 and KISS1R have been shown to be highly expressed in mesenchymal stem cells in multiple myeloma." (PMID 30046386, 2018).
ovarian diseases (1 paper, 2019). "The genes KISS1 and FSHR were related to ovarian diseases like POF and PCOS43,44." (PMID 31745224, 2019).
pancreatic adenocarcinoma (1 paper, 2018). "Pancreatic cell lines such as BxPC-3, PANC-1 and SUIT-2 express low levels of endogenous KISS1, thus KISS1 was overexpressed in a metastatic subclone of the SUIT-2 pancreatic adenocarcinoma cell line, S2VP10." (PMID 30123188, 2018).
pancreatic ductal adenocarcinoma (1 paper, 2014). An infiltrating adenocarcinoma that arises from the epithelial cells of the pancreas. "Inactivation of KiSS1 by promoter methylation is an infrequent event in pancreatic ductal adenocarcinoma (PDAC)." (PMID 25272010, 2014).
Parkinson disease (1 paper, 2025). A progressive degenerative disorder of the central nervous system characterized by loss of dopamine producing neurons in the substantia nigra and the presence of Lewy bodies in the substantia nigra and locus coeruleus. "The research showed that STAT4 regulated the transcription of KISS1 to inhibit the oxidative damage, inflammation and neuronal apoptosis in the model of Parkinson’s disease." (PMID 40214477, 2025).